CDKN2A (cyclin dependent kinase inhibitor 2A)
Diseases named in the same sentence as CDKN2A in open-access papers (continued):
Sharing a sentence is not in itself a finding about the gene and the disease.
tumor (continued). "Both MUG-Myx2 cell lines showed a similar pattern of CNVs in these genes and shared the distinct loss of CDKN2a and MLH1, as well as a gain of FGFR1, with the primary tumor tissue." (PMID 28304377, 2017). "PRC1 has been linked to the repression of certain tumor suppressor genes, such as PTEN and INK4a/ARF (CDKN2A), in carcinoma cells." (PMID 29050200, 2017). "CDKN2A has been shown as a tumor suppressor in cancer progression, and its alterations, including epigenetic modifications, deletion, and mutations, frequently occur in cancers." (PMID 29285217, 2017). "Mutation frequency in tumor tissues from rb1 TALEN-injected F0 tp53e7/e7 zebrafish varied from 66.6% (32/48) to 83.3% (40/48), while the frequency in cdkn2a/b TALEN-injected F0 tp53e7/e7 zebrafish varied from 81.3% (39/48) to 91.6% (44/48)." (PMID 28903419, 2017). "Immunostaining with anti-phospho-Histone3(H3) antibodies demonstrated that tumor tissue of cdkn2a/b TALEN mRNA injected tp53e7/e7 mutant zebrafish had highly mitotic cells (2A’)." (PMID 28903419, 2017). "ERMS tumor also harbored additional gene alterations: low amplification of EGFR, PDGFRA, and CDK4 genes, and loss of heterozygosity of CDKN2A and 19q12-19q13.43 chromosomal regions." (PMID 28222777, 2017). "The SNP rs3731249 is a missense SNP in CDKN2A which produces an alanine-to-threonine change in amino-acid-sequence, resulting in reduced tumor suppressor function of p16INK4A." (PMID 28481918, 2017). "The methylation status of CDKN2A exon 2 in tumors was significantly higher than in tumor-adjacent (p < 0.001) and tumor-distant tissues (p < 0.001) from the same patients and in normal breast tissues from healthy women (p < 0.001)." (PMID 28403857, 2017). "Kaplan–Meier survival curves also represented that cdkn2a/b-TALEN mRNA injection lead tp53e7/e7 mutant zebrafish to early death with tumor bearing compared to non injected mutant zebrafih, remarkably (P < 0.0001)." (PMID 28903419, 2017). "P16, consisting of an alternative reading frame of cyclin-dependent kinase inhibitor 2A (CDKN2A), is thought to function as a tumor suppressor by negatively regulating the cell cycle and inhibiting cell proliferation." (PMID 28977861, 2017). "Several tumor-suppressors, including p16INK4A and CDKN2A, have been reported to have the reduced expression due to the retain H3K27me3 activity in H3K27M induced DIPG tumors." (PMID 29118968, 2017).
tumor (continued). "In contrast, exon 2 of CDKN2A showed a methylation status ≥ 25% in 78% (14/18) of the tumors and 11% (2/18) of the tumor-adjacent and tumor-distant tissues." (PMID 28403857, 2017). "We further analyzed tumor tissues from cdkn2a/b-TALEN mRNA injected tp53e7/e7 mutant zebrafish with immunostaining methods." (PMID 28903419, 2017). "Subsequently, we evaluated the effect of tumor histology, asbestos exposure, CDKN2A deletion status, and gender on the gene expression level of the claudin interactome." (PMID 28377727, 2017). "The cyclin-dependent kinase inhibitor 2A (CDKN2A) gene on chromosome 9p21 is a classical tumor suppressor gene." (PMID 28637022, 2017). "Our long-term follow-up of in vivo growth of IC-3635PXA tumors revealed a clear enrichment of BRAF V600E mutation frequency and detected a novel a shift of diploid chromosome 9 to trisomy 9 in tumor cells bearing CDKN2A deletion." (PMID 29152094, 2017). "Under the same conditions, injection of cdkn2a/b-TALEN mRNA led to an increase in tumor incidence frequency up to about 39% and accelerated tumor onset as early as 35 to 37 wpf in tp53e7/e7 mutant zebrafish." (PMID 28903419, 2017). "Molecularly, xenograft cells with homozygous deletion of CDKN2A shifted from disomy chromosome 9 to trisomy chromosome 9; and BRAF V600E mutation allele frequency increased (from 28% in patient tumor to 67% in passage III xenografts)." (PMID 29152094, 2017). "NOTCH1, CDKN2A, FBXW7, FAT1, and ZNF750 were considered as tumor suppressors and showed recurrent inactivating mutations." (PMID 29348864, 2017). "The CDKN2A is a tumour suppressor involved in multiple cancers and controls the cell cycle and proliferation." (PMID 28676692, 2017). "Previously, in a genetically engineered MM mouse model, heterozygous for Nf2+/−, a high rate of homozygous deletion of Cdkn2a was observed in MM tumours induced by asbestos exposure." (PMID 28577549, 2017). "In this study, we developed somatically mutated tumor models using TALEN-mediated somatic gene inactivation of cdkn2a/b or rb1 tumor suppressor genes in zebrafish." (PMID 28903419, 2017). "In the course of developing tumor suppressor gene knockout progeny, we observed that somatic gene inactivation of cdkn2a/b and/or rb1 efficiently induced tumors in the F0 founder generation." (PMID 28903419, 2017). "Inactivation of COX-2, HMLH1 and CDKN2A by promoter methylation depends on the Helicobacter pylori genotype and occurs by distinct pathways, according to the histological subtype and tumor location." (PMID 28418867, 2017). "CDKN2A was the dominant homozygously deleted tumour suppressor, with 108 homozygous deletions across nine cancer types." (PMID 29089486, 2017). "CDKN2A products have important tumour suppression roles so if breastfeeding really does increase CDKN2A expression via epigenetic changes, then it has the potential to protect against cancer." (PMID 28257446, 2017). "Activation of the Wnt pathway induces therefore an increased expression of negative regulators of the cell cycle such as the tumour suppressors Cdkn2a (p16Ink4a, p19Arf) and Cdkn2b (p15Ink4b)." (PMID 28346462, 2017). "Methylation levels of the BRCA1 promoter strongly correlated with those of the CDKN2A promoter in tumors (r = 0.990, p < 0.001), tumor-adjacent tissues (r = 0.920, p < 0.001) and tumor-distant tissues (r = 0.963, p < 0.001)." (PMID 28403857, 2017).
tumor (continued). "WES of this second tumor recurrence again showed chromosome 10 and CDKN2A deletion but even more interestingly still high ploidy of the EGFR/MDM4 loci (>10 and >6, respectively)." (PMID 28153049, 2017). "Deletions in cyclin-dependent kinase inhibitor 2A (CDKN2A) locus is a common mutation in T-ALL; so, CDKN2A tumor suppressor locus is disrupted in 90% of T-ALL cases." (PMID 28580304, 2017). "She underwent a second gross total resection in March, and WES of this recurrent tumor revealed a similar profile to the primary tumor with amplification of chromosome 7 and deletions of chromosome 10 and the CDKN2A locus on chromosome 9." (PMID 28153049, 2017). "Significant correlations were found between the proliferative activity and the methylation status of CDKN2A exon 2 in tumor (r = −0.485, p = 0.041) and tumor-distant tissues (r = −0.498, p = 0.036)." (PMID 28403857, 2017). "The most significant region was a homozygous deletion encompassing the tumour suppressor gene Cdkn2a which was evident in all 15 murine MM tumour cell lines (q = 5 × 10−17)." (PMID 28577549, 2017). "Other known aberrations, such as loss of chromosome 10, were also observed and deletion of the tumour suppressor gene CDKN2A on chromosome 9p21.3, was seen in all tumours except GB180." (PMID 28655341, 2017). "In tumors, CDKN2A exon 2 was significantly higher methylated than in tumor-adjacent and tumor-distant tissues." (PMID 28403857, 2017). "CDKN2A (p16INK4a), located on chromosome 9p21, is an important tumor suppressor and DNA repair gene and functions as a major negative regulator of critical tumor pathways." (PMID 28316892, 2017). "Most known oncogenes (e.g. EGFR, FGFR1, MYC, ERBB2) or tumor suppressors (e.g. CDKN2A, NOTCH1) were detected to reside within the focal SCNA regions." (PMID 29348864, 2017). "The proteins encoded by CDKN1A and CDKN2A can inhibit the activity of cyclin-CDK and function as tumor suppressors to control cell cycle in HBV-related HCC." (PMID 29191172, 2017). "CDKN2A is a tumor suppressor gene and is frequently inactivated in human cancers by hypermethylation of its promoter." (PMID 28637022, 2017). "Overexpression of UHRF1 occurs in many types of cancer, and aberrantly expressed UHRF1 causes cancer cell activation through hyper-methylation of tumor-suppressor genes such as BRCA1, CDKN2A, p73, and RASSF1." (PMID 27072587, 2016). "Our results showed that after 1 week of MycN knockdown, there was significant increase in the expression of well-recognized tumor suppressors that induce G1 cell cycle arrest, such as Cdkn1a, Cdkn2a and Cdkn2b." (PMID 26815535, 2016). "Consistently, we have illustrated that MycN knockdown in human NCSCs increased the expression of Cdkn1a, Cdkn2a and Cdkn2b, emphasizing the critical role of these tumor suppressors in stem cell growth and cell cycle progression." (PMID 26815535, 2016). "In the study (Bulavin and colleagues) the absence of inhibitory effect of Wip1 on p38 leads to elevated levels of two products of Cdkn2a gene, p16 and p14arf, which were responsible for tumor suppression in mammary gland epithelium." (PMID 26883196, 2016). "CDKN2A, also known as cyclin-dependent kinase inhibitor 2A, codes for two proteins, including p16 an p14arf, both act as tumor suppressors by regulating the cell cycle." (PMID 27167196, 2016).
tumor (continued). "Tumor budding was characterized by increased expression for both β-catenin and p16 (cyclin-dependent kinase inhibitor 2A)." (PMID 27843459, 2016). "Genetic alterations on chromosome 9p, including inactivation of the tumour suppressor gene, CDKN2A, result in cellular proliferation and growth of tumours." (PMID 27682877, 2016). "CDKN2A is also frequently methylated (23–67 % of cases;) to silence expression of this tumor suppressor; although, degree of methylation and expression changes can vary significantly among individual tumors." (PMID 29034103, 2016). "Hypermethylated CDKN2A promoter sequences were observed in 80.2% of tumor tissues by MSP, as a function of several patient-, disease- or technical-related factors." (PMID 27517925, 2016). "The RB tumor suppressor pathway is frequently altered through deletion of CDKN2A (p16; ∼35%) or amplification of CCND1 (cyclin D1; ∼94%) in HNSCC." (PMID 26909611, 2016). "Uniquely, the tumor suppressors CDKN2A and PTEN show robustly significant differences between focal and broad losses within amplitude bins, with the exception of the most shallow PTEN bin (>−0.58)." (PMID 26787600, 2016). "MHI-null mice developed tumors with a short latency (3.95 months), while mice heterozygous for the Cdkn2a locus (MHI-het) showed delayed tumor formation (6 months)." (PMID 26987019, 2016). "Tumour suppressor genes CDKN2A (encoding p16INK4a), ARF (encoding p14ARF), and CDKN2B (encoding p15INK4b) residing on chromosome 9p21 are all associated with the anaplastic grade." (PMID 27429002, 2016). "The methylthioadenosine phosphorylase (MTAP) gene is located at 9p21 and is flanked by the tumor suppressor miR-31 and the cyclin-dependent kinase inhibitor 2A (CDKN2A) gene, which are approximately 100 kb away." (PMID 26751376, 2016). "The RB pathway was considered disrupted in a tumor if one of the following events occurred: 1) RB1 mutation/homozygous deletion/underexpression; 2) CDKN2A mutation/homozygous deletion/underexpression; or 3) CCND1 overexpression." (PMID 27832204, 2016). "The normal activity of the CDKN2A (also known as p16) gene is as a tumor suppressor, preventing uncontrolled cell proliferation by initiating cell cycle arrest and apoptosis." (PMID 25879218, 2015). "The cascade of events leading to tumor development was accompanied by a notable decrease in the mRNA level of Cdkn2A, a tumor suppressor gene." (PMID 26322231, 2015). "CDKN2A/p16INK4a is an essential tumor suppressor gene that controls cell cycle progression and replicative senescence." (PMID 26498684, 2015).
tumor (continued). "No known oncogenes were found mutated, but four of the seven patients (GIST_150, _174, _124 and _188) showed deleterious mutations in two candidates (KEAP1 and LATS2) and in three well-known tumor suppressors (CDKN2A, CDKN1B and PTEN)." (PMID 26544626, 2015). "In the current study, we have used 2 major databases to identify a compound, TGX221 not previously studied in ccRCC that has strong selectivity for tumours having VHL, SETD2, PTEN and CDKN2A mutations." (PMID 25853938, 2015). "As expected, one of the most significantly expressed genes in HPV+ tumor tissue was CDKN2A, which encodes for p16INK4A." (PMID 26334652, 2015). "CDKN2A/p16INK4a (herein indicated as p16INK4a) is a critical tumor suppressor that inhibits the cyclin-dependent kinases CDK4 and CDK6, thereby keeping the retinoblastoma protein (pRB) in a hypo-phosphorylated state, thus leading to G1/S checkpoint activation." (PMID 26498684, 2015). "CDKN2A, PIK3CA, RASA1 and DMD variants were exclusively linked to smoking, chewing, HPV infection and tumor stage." (PMID 26834999, 2015). "Cyclin dependent kinase inhibitor 2a and 2b (CdkN2a and 2b), p107 and N-ras were all significantly over-expressed in TAg tumours relative to wild type tumours." (PMID 26680231, 2015). "Other variants related to tumor biology included a homozygous BRAF p.V600E mutation in THJ-21T and heterozygous and homozygous frame-shift deletions of HDAC10 (p.H134Tfs) and CDKN2A (p.Q70Sfs), respectively, in THJ-29T." (PMID 26680454, 2015). "Tumor suppressor CDKN2A gene is located on chromosome 9p21, which is one of the crucial defenses against cancer development." (PMID 26338139, 2015). "Overexpression of CDK4/6 or D-type cyclins and inactivation of the CDK4/6 antagonist p16INK4A/CDKN2A or Rb tumour suppressor are common in human cancer." (PMID 25562820, 2015). "Tumors from WT mice had higher HDAC levels globally and locally on genes such as cyclin-dependant kinase inhibitor 2a (Cdkn2a/p16) that were dysregulated during tumor development." (PMID 26388957, 2015). "The additional 120 central conventional cartilaginous tumours from 120 different patients were analysed for p16/CDKN2A by FISH." (PMID 25432631, 2015). "In 3, the primary tumour showed normal copy number, and progression to a higher morphological grade (GII to GIII) was accompanied by p16/CDKN2A loss." (PMID 25432631, 2015). "For example, the mechanism(s) of repression of CDKN2A, which is alternatively spliced to produce the p16INK4 and p14ARF tumor suppressors, will need to be reexamined for potential post-transcriptional effects of TBX3." (PMID 24675841, 2014). "In univariable analysis, tumor stage (log rank P = 0.006) and grade (P < 0.001), HPV DNA (P < 0.004), Chromosome 9 loss (P = 0.04) and the A148T polymorphism (rs 3731249) in CDKN2A (P = 0.02) were associated with progression." (PMID 25142434, 2014). "Among the CIMP genes are three well-known tumor suppressors: p14ARF, p16INK4A (also known as CDKN2A), and p15INK4B (also known as CDKN2B)." (PMID 24623306, 2014). "Molecular characterization of the tumor demonstrated a well-described BRAF V600E point mutation and loss of CDKN2A/B." (PMID 25563358, 2014).